TYW3 (tRNA-yW synthesizing protein 3 homolog)
Description:
S-adenosyl-L-methionine-dependent methyltransferase involved in the biosynthesis of wybutosine, a hyper modified guanosine with a tricyclic base located at position 37 of eukaryotic phenylalanine tRNA (tRNA(Phe)) that contributes to maintenance of the translational reading frame. Catalyzes the methylation of 4-demethylwyosine, generating intermediates required for the formation of mature wybutosine.
Synonyms: C1orf171; FLJ40918
Tractability: Antibody: the Human Protein Atlas places it where antibodies can reach. PROTAC: ubiquitination databases record sites on it.
Gene: Protein-coding gene on chromosome 1 (74,733,152 to 74,767,555, forward strand). Ensembl gene ENSG00000162623.
Subcellular location (Human Protein Atlas): Cytosol; Plasma membrane
Pathways (Reactome):
Metabolism of RNA: Synthesis of wybutosine at G37 of tRNA(Phe)
Gene Ontology:
Molecular function: protein binding
Biological process: wybutosine biosynthetic process
Cellular component: cytoplasm
Genetic constraint (gnomAD): Loss-of-function variants: 21 observed, 18.23 expected, observed/expected ratio (o/e) 1.15, 90% interval 0.82 to 1.65. The upper end of that interval is the gene's LOEUF score, 1.65, which puts it in group 6 of 6, group 1 being the genes least tolerant of losing a copy. Missense variants: 294 observed, 292.59 expected, observed/expected ratio (o/e) 1, 90% interval 0.91 to 1.11. Synonymous variants: 94 observed, 101.11 expected, observed/expected ratio (o/e) 0.93, 90% interval 0.79 to 1.1.
Homologues: Orthologues: chimpanzee TYW3 (99% identical), macaque TYW3 (92% identical), dog TYW3 (83% identical), pig TYW3 (83% identical), rabbit TYW3 (80% identical), rat Tyw3 (70% identical), mouse Tyw3 (70% identical), zebrafish tyw3 (52% identical), tropical clawed frog tyw3 (49% identical). Paralogues in human: TYW2 (15% identical), TRMT5 (13% identical).
Diseases named in the same sentence as TYW3 in open-access papers:
TYW3 is named in the same sentence as 8 diseases in open-access papers, as found by Europe PMC text mining. Sharing a sentence is not in itself a finding about the gene and the disease. The quoted sentences say what the papers report.
amyotrophic lateral sclerosis (2 papers, 2024). Amyotrophic lateral sclerosis (ALS) is a neurodegenerative disease characterized by progressive muscular paralysis reflecting degeneration of motor neurons in the primary motor cortex, corticospinal tracts, brainstem and spinal cord. "TYW3 gene has been previously found associated with amyotrophic lateral sclerosis (ALS) and tic spectrum disorder (TSD)." (PMID 39514604, 2024).
Insulin resistance (2 papers, 2018 to 2022). Increased resistance towards insulin, that is, diminished effectiveness of insulin in reducing blood glucose levels. "CRYZ encodes for zeta-crystallin, nicotinamide-adenine dinucleotide phosphate-dependent quinone reductase, and TYW3 for tRNA-wybutosine synthesis protein 3 homolog, two metabolic proteins associated with insulin resistance, a clinical feature with a high prevalence to PD." (PMID 35883433, 2022).
gastric cancer (1 paper, 2016). A primary or metastatic malignant neoplasm involving the stomach. "OR3A4, LOC84740, FCGR1C, and NCRNA00200 were overexpressed in gastric cancer tissues, whereas MSTO2P, LOC344595, TUG1, and TYW3 were downregulated." (PMID 26863570, 2016). "OR3A4, LOC84740, FCGR1C, and NCRNA00200 were upregulated in gastric cancer tissues, whereas MSTO2P, LOC344595, TUG1, and TYW3 were downregulated (P < 0.05)." (PMID 26863570, 2016).
TYW3 also shares sentences with these, for which no sentence is quoted: cancer (2 papers); astrocytomas (1); cardiovascular disease (1); metabolic syndrome (1); type 2 diabetes (1).